CD274 (CD274 molecule)
Diseases named in the same sentence as CD274 in open-access papers (continued):
Sharing a sentence is not in itself a finding about the gene and the disease.
cholangiocarcinoma (99 papers, 2016 to 2026). A carcinoma that arises from the intrahepatic biliary tree (intrahepatic cholangiocarcinoma) or from the junction, or adjacent to the junction, of the right and left hepatic ducts (hilar cholangiocarcinoma). "GEM-based chemotherapy induced immunogenic cell death of cholangiocarcinoma cells, together with increased CD274 expression." (PMID 36159865, 2022). "Similar to the RBE cell line, in the cholangiocarcinoma cell line HuCCT1, BEX2 or CD274 expression was mutually exclusive." (PMID 33299012, 2020). "We previously reported that CD274, also known as PD-L1, suppresses CSC phenotypes in cholangiocarcinoma." (PMID 33299012, 2020). "To investigate gene(s) responsible for dormant cancer stem cells enriched in the CD274low fraction of cholangiocarcinoma cells, we screened genes differentially expressed between CD274-knockdown and control RBE cholangiocarcinoma cells." (PMID 33299012, 2020). "We analyzed differential gene expression in CD274-knockdown and control cells and identified BEX2, whose expression is mutually exclusive to CD274 expression in a variety of cancer cells, including cholangiocarcinoma cells." (PMID 33299012, 2020). "To test whether the generalized MLR is able to predict CD274 levels in cancer types other than BRCA, LUAD, or SKCM, we used data from a total of 36 patients with cholangiocarcinoma (CHOL), and 165 patients with rectum adenocarcinoma (READ)." (PMID 35289334, 2022). "Similarly CD274, another CSC marker of relevance, showed useful results in a study focusing on CD274 (PD-L1) in cholangiocarcinoma through in vivo and in vitro experiments." (PMID 30072631, 2018).
cutaneous melanoma (99 papers, 2013 to 2025). A primary melanoma arising from atypical melanocytes in the skin. "Here, we evaluated the expression of CD274 (PD-L1) along with other immunoinhibitors and immunostimulators, across TMBhigh, TMBint and TMBlow skin melanomas." (PMID 36389735, 2022). "For example, PD-1 (encoded by PDCD1) and PD-L1 (encoded by CD274), a well-defined immunosuppressive axis in the TME, were found to be correlated with SPHK1 expression in most cancer types, including skin cutaneous melanoma (SKCM)." (PMID 36050478, 2022). "Furthermore, CD274 (PD-L1) expression correlated significantly with the rest immune checkpoints (apart from VTCN1) in skin melanoma compared to normal skin (not exposed to the sun), especially with PD-L2, ILT2, HAVCR2 and TIGIT." (PMID 36389735, 2022).
gastric adenocarcinoma (95 papers, 2016 to 2026). "To further confirm those findings, we analyzed a TCGA stomach adenocarcinoma tissue dataset (n = 269) and found that cases with CD274 amplification showing high expression of CD274 mRNA were common in EBV (+) GC." (PMID 33479394, 2021). "Our analysis revealed that there was a significant positive association between TUBA1C and CD274 in several cancer types, including KIRC, kidney renal papillary cell carcinoma (KIRP), stomach adenocarcinoma (STAD), and breast invasive carcinoma (BRCA), among others." (PMID 39301023, 2024).
Hepatitis (91 papers, 2012 to 2025). Inflammation of the liver. "CNVs on IL1RN and deletions on PRDM1 were significantly linked to IRAE, whereas duplications on CD274 and CNVs on SLCO1B1 were significantly linked to hepatitis." (PMID 35053465, 2022). "CNVs on CD274 (PD-L1) were a recurrent marker for IRAE, being significantly linked to hepatitis, encephalitis and myositis." (PMID 35053465, 2022). "Duplications on CD274 (p = 0.043) and CNVs on SLCO1B1 (p = 0.010) were significantly linked to hepatitis." (PMID 35053465, 2022). "Furthermore, the following genetic alterations were identified being associated with IRAE: SMAD3 (pancreatitis); CD274, SLCO1B1 (hepatitis); PRDM1, CD274 (encephalitis); PRDM1, CD274, TSHR, FAN1 (myositis)." (PMID 35053465, 2022). "Regarding CNVs, significant markers included PRDM1 deletions and IL1RN (IRAE), CD274 duplications and SLCO1B1 (hepatitis), PRDM1 and CD274 (encephalitis), and PRDM1, CD274, TSHR, and FAN1 (myositis)." (PMID 35053465, 2022).
brain tumors (87 papers, 2014 to 2026). "It should be noted that, in addition to PD-L1, another PD1 ligand, the programmed cell death ligand-2 (PD-L2/CD274) is emerging as clinically relevant in primary brain tumors." (PMID 34572014, 2021). "Finally, we reproduced the overall known poor infiltration of CD8+ T cells and general low expression of CD274 (PD-L1) in pediatric brain tumors, highlighting that we urgently need novel therapeutic strategies for tumors unlikely to respond to immune checkpoint blockade therapy." (PMID 37492101, 2023). "We hypothesized that AQP4 could also be the regulatory factors of various immune checkpoints in brain tumors, such as TIM-3 (HAVCR2), PD-L1 (CD274), PD-L2 (PDCD1LG2), and CEACAM1." (PMID 34113257, 2021).
oral cancer (86 papers, 2015 to 2026). "By using GSE42734 dataset, we found that the mRNA levels of FOXD1 and PD-L1-coding gene CD274 are positively correlated in primary tumors derived from oral cancer patients." (PMID 32967107, 2020). "In particular, the regulation of CD274 and PDCD1LG2 in oral cancer cells induced by P. gingivalis was recently reviewed as a part of important mechanisms involved in the association between oral bacteria and cancer, which was consistent with our findings." (PMID 28286742, 2017). "The low expression of three ICGs positively correlated with CD274 (BTLA, CD27, and CTLA4) indicated a better prognosis compared to their high expression, indicating their coinhibitory roles in the tumor immunology of oral cancer." (PMID 35127742, 2021).
intrahepatic cholangiocarcinoma (75 papers, 2017 to 2026). A carcinoma that arises from the intrahepatic bile duct epithelium in any site of the intrahepatic biliary tree. "Single-cell transcriptomics shows that intrahepatic cholangiocarcinoma (ICC) cells susceptible to cuproptosis are typically CD274 (PD-L1)-negative and reside in a TME with reduced monocytes and macrophages." (PMID 41355954, 2026). "Case 3 is an adult patient with intrahepatic cholangiocarcinoma (stage IVB, T2N1M1) with positive PD-L1 expression and disruption of the CD274 3' UTR region." (PMID 36717553, 2023). "Furthermore, in intrahepatic cholangiocarcinoma (ICC), myofibroblastic CD274 plays a crucial role in modulating both the tumor microenvironment and tumor growth, independent of immune suppression function." (PMID 36009475, 2022).
rectal cancer (73 papers, 2017 to 2026). A primary or metastatic malignant neoplasm that affects the rectum. "0.3% of samples were CD274‐altered in both colon and rectal cancer, respectively." (PMID 39865537, 2025).
T-cell lymphoma (72 papers, 2014 to 2025). "Case 8 is an adult patient with mature T-cell lymphoma with positive PD-L1 expression and fusion in the CD274 5' UTR region." (PMID 36717553, 2023). "STAT3 is commonly activated in tumor-infiltrating macrophages, and STAT3 can bind to the promoter of the CD274 gene required for PD-L1 gene expression in T-cell lymphoma." (PMID 33509150, 2021). "Mouse and human T cell lymphoma cells express PD-L1 in the steady state, and Stat3 binds to the promoter region of the Cd274 gene encoding PD-L119,22,23." (PMID 29728568, 2018). "Its ligands, PD-L1 (B7-H1, CD274) and PD-L2 (B7H3, CD273), are also often expressed by the tumor cells in some B cell or T cell lymphoma." (PMID 28402953, 2017).
colon adenocarcinoma (70 papers, 2017 to 2026). "Notably, higher expressions of CTLA4 and PD1 were associated with improved survival, while higher TIL load correlated with CTLA4, HAVCR2 (TIM-3), LAG3, and CD274 (PD-L1) expressions in colon adenocarcinoma." (PMID 35804964, 2022).
thymoma (70 papers, 2017 to 2026). A neoplasm arising from the epithelial cells of the thymus. "We found high expression of CD274 (PD-L1) in B2 and B3 thymoma samples, and validated its expression using immunohistochemistry (IHC)." (PMID 34568003, 2021). "Immune checkpoints like CTLA4, CD274 (PD-1), and PDCD1 (PD-L1) were highly expressed in high-CD3E and high-LCK groups for MIBC and also for pan-cancers, except for thymoma." (PMID 35004669, 2021). "Notably, SHROOM2 expression was positively correlated with PD-L1 (CD274) in BRCA, CESC, COAD, COADREAD, GBM, KICH, kidney renal papillary cell carcinoma (KIRP), LGG, LIHC, LUSC, PRAD, SARC, STES, TGCT, thymoma (THYM), and Wilms tumor (WT)." (PMID 41025048, 2025). "Notably, CD274 expression was substantially connected with patients' overall survival in 6 distinct cancers, which were LGG (brain lower grade glioma), SKCM, THYM (thymoma), PAAD, OV, and TGCT." (PMID 38166842, 2024).
type 1 diabetes (70 papers, 2014 to 2026). "Cytokines and ER stress are reported triggers of PDL1 (also known as CD274) expression in beta cells, which occurs in type 1 diabetes." (PMID 38864887, 2024). "Healthy subjects had higher levels of galectin-10, CD24, CD197, CD196, CD25 and CD45RO and patients with type 1 diabetes had higher levels of CD16, CD45RA, CD274, HLA-DR, CD28, Interleukin (IL)-5R, and CD38." (PMID 37210405, 2023).
colorectal tumors (65 papers, 2014 to 2025). "For example, one study found that PIK3CA gene mutations activate the PI3K pathway, which is associated with the overexpression of CD274 (PD-L1) in colorectal tumor tissues, supporting the role of PI3K signaling in the upregulation of CD274." (PMID 39555098, 2024). "The colorectal tumors expressing CD274(PD-L1) was reported that associated with poorly prognostic factors such as poorly differentiation, BRAF mutation and ‘stem-like’ immunophenotype features." (PMID 29108360, 2017). "Utilizing the TIMER2.0 database, overexpression of PDIA3 in colorectal tumors was initially identified, and further confirmed through GEO database analysis, establishing a strong correlation between PDIA3, STAT3, and CD274." (PMID 38761176, 2024).
urothelial bladder cancer (64 papers, 2010 to 2026). "This study demonstrated that the combined biomarker of APOBEC3B and CD274 was more effective in predicting the response to PD-1/PD-L1 inhibitors than a single biomarker of CD274 in bladder urothelial carcinoma." (PMID 36245972, 2022). "In GSE70120, bladder transitional cell carcinoma (UM-UC-3) also showed significantly increased expression of CD274 and significantly high expression of MHC molecules and coinhibitory and costimulatory molecules." (PMID 34635662, 2021). "Moreover, the combined biomarkers of A3B and CD274 were more effective in predicting response to immunotherapy in bladder urothelial carcinoma." (PMID 36245972, 2022). "CD274 expression was found to influence patients' DFI (disease-free interval) in six cancer types, which were LGG, SKCM, PAAD, OV, TGCT, and BLCA(bladder urothelial carcinoma)." (PMID 38166842, 2024).
tuberculosis (60 papers, 2010 to 2026). A chronic, recurrent infection caused by the bacterium Mycobacterium tuberculosis. "The diagnostic potential of CD274, IRF1 and HPSE in active tuberculosis (ATB) is supported by their strong positive correlation with neutrophil infiltration, as shown in validation datasets (GSE62525 and GSE28623)." (PMID 40607433, 2025). "In addition, it has been shown that 10 biomarkers, including CD274 and EGF, can be used for the diagnosis of tuberculosis, the differential diagnosis of latent tuberculosis infection/active tuberculosis, and the risk of progression to active tuberculosis." (PMID 36793717, 2023). "This is especially interesting because neutrophils from patients with active tuberculosis also exhibit an IFN-induced transcriptome profile, including increased expression of CXCL10 and CD274." (PMID 24015224, 2013).
rheumatoid arthritis (57 papers, 2014 to 2026). A chronic, systemic autoimmune disorder characterized by inflammation in the synovial membranes and articular surfaces. "The association with CD274 that encodes the ligand for the PD‐1 receptor is further support for a key role of PD‐1 signaling in rheumatoid arthritis." (PMID 39887658, 2025).
thyroiditis (57 papers, 2018 to 2026). Inflammation of the thyroid gland. "By targeted sequencing of this gene panel in MALT lymphoma of various sites, we have identified highly frequent inactivating mutations of both CD274 (PD-L1) and TNFRSF14 in thyroid MALT lymphoma." (PMID 34021249, 2021). "PD-L1 immunohistochemistry showed no detectable protein expression in the tumour cells of 51 thyroid MALT lymphomas investigated including 35 cases with CD274 mutation/deletion." (PMID 34021249, 2021).
meningioma (54 papers, 2015 to 2026). A generally slow growing tumor attached to the dura mater. "Other inflammatory microenvironment elements have been associated with meningioma grade – for example, the immune modulatory molecule PD-L1 (CD274, which has an immune avoidance role) has been associated with anaplastic meningiomas." (PMID 31039818, 2019). "In 2014, Du and colleagues analyzed lymphocyte infiltration and the expression of PD-L1 (CD274) in a large cohort of 291 meningioma samples (n = 195 WHO°1, n = 73 WHO°2 and n = 23 WHO°3)." (PMID 39273576, 2024).
thymic carcinoma (51 papers, 2016 to 2025). Thymic carcinoma (TC) is a type of thymic epithelial neoplasm characterized by a high malignant potential. "In thymic carcinoma, pathogenic CYLD variants were associated with increased PD-L1 (CD274) levels and better response to immune checkpoint inhibitor therapy." (PMID 37387450, 2023).
psoriasis (49 papers, 2014 to 2025). An autoimmune condition characterized by red, well-delineated plaques with silvery scales that are usually on the extensor surfaces and scalp. "Another study showed that CD274 was the regulator of the indirubin-mediated effect on mouse psoriasis-like skin lesions based on co-expression network analysis, contributing to the alleviation of mouse psoriasis-like skin lesions." (PMID 39296901, 2024). "Current studies have shown that indirubin has a dose-dependent therapeutic effect on alleviating psoriasis-like skin lesions in mice, among which CD274 is a regulatory factor of indirubin-mediated effect on psoriasis-like skin lesions in mice." (PMID 36466901, 2022). "It has been confirmed that indirubin can attenuate the epidermal thickness of psoriasis-like skin lesion in mice by regulating CD274." (PMID 32795328, 2020). "It was previously reported that the expression of CD274 was down-regulated in psoriatic epidermis, leading to immune disorders of psoriasis." (PMID 30341238, 2018). "We demonstrated for the first time that CD274 was the regulator of indirubin-mediated effect on mouse psoriasis-like skin lesion based on co-expression network analysis, contributing to the alleviation of mouse psoriasis-like skin lesion." (PMID 30341238, 2018). "Our study found a strong link between CD274 and the development of psoriasis." (PMID 40557155, 2025). "In psoriasis, the expression of CD274 may regulate the activation of immune cells and inflammatory responses, thus influencing the development of psoriasis." (PMID 40557155, 2025). "We raised a hypothesis that CD274 was the regulator of indirubin-mediated effect on mouse psoriasis-like skin lesion, which contributed to the alleviation of mouse psoriasis-like skin lesion." (PMID 30341238, 2018). "Tumor patients were reported to induce psoriasis under the treatment of CD274 antibody." (PMID 30341238, 2018). "These previous studies indicated the vital role of CD274 in psoriasis." (PMID 30341238, 2018). "Indirubin has been demonstrated to increase the expression of CD274 in human epidermal keratinocytes, we then detected whether CD274 was involved in the alleviative effect of indirubin on psoriasis." (PMID 30341238, 2018). "Indirubin could increase the level of CD274 in epidermal keratinocytes and alleviate the symptom of psoriasis-like mice depending on CD274, indicating the value of indirubin in the treatment of psoriasis." (PMID 30341238, 2018). "Decreased CD274 protein was considered to involve the immune disorders of psoriasis." (PMID 30341238, 2018). "Therefore, CD274 (PD-L1) may be involved in regulating the activity of the IL-17a and IL-23 pathways in psoriasis, affecting autoimmune reactions and the occurrence of inflammation." (PMID 40557155, 2025). "Therefore, drugs increasing the level of CD274 in keratinocytes may serve as a potential therapeutic strategy in the treatment of psoriasis." (PMID 30341238, 2018). "The ROC curves demonstrated that the expression levels of eight Hub Genes—POSTN, CD274, CD24, SERPINB3, CXCL13, SMPD3, BIRC5, and RAB27A—exhibited high accuracy (AUC > 0.9) in classifying the Psoriasis and Control groups." (PMID 40557155, 2025). "Sixteen exosome-related differentially expressed genes (ERDEGs), including CD274 and SERPINB3, are likely to play a significant role in the development of psoriasis." (PMID 40557155, 2025). "Some studies indicate that CD274 (PD-L1), CXCL13, BIRC5, and SMPD3 are important in the pathogenesis of psoriasis." (PMID 40557155, 2025). "Further animal experiments demonstrated that CD274 could serve as one of the effector molecules of indirubin, a CDK1 inhibitor, against psoriasis." (PMID 30341238, 2018).
metastatic colorectal cancer (44 papers, 2016 to 2026). "In summary, we found genetic variant of CD274:rs2297136 was related to the clinical outcome of metastatic colorectal cancer (mCRC) patients treated with bevacizumab-based chemotherapy." (PMID 35837092, 2022).
pulmonary fibrosis (44 papers, 2017 to 2026). Chronic progressive interstitial lung disorder characterized by the replacement of the lung tissue by connective tissue, leading to progressive dyspnea, respiratory failure, or right heart failure. "A previous report showed that CD274 knockdown in IPF fibroblasts by FAK inhibition or CD274-neutralizing antibodies, reduced invasion and alleviated fibrosis, whereas PD-L1 expression on invasive fibroblasts promoted lung fibrosis." (PMID 38263193, 2024). "In the context of IPF and bleomycin-induced lung fibrosis, CD274 induction plays a role in the SMAD3/GSK3-mediated fibroblast to myofibroblast fate induction and collagen deposition, and in the IPF fibroblasts’ invasive properties." (PMID 35626630, 2022). "In the IPF model, fibroblast-intrinsic CD274 is required for the development of pulmonary fibrosis through interaction with SMAD3, resulting in further activation of the Wnt-/βCathenin pathway." (PMID 36009475, 2022). "We recently discovered that the immune checkpoint ligand PDL1 (CD274) was upregulated on invasive fibroblasts and targeting PDL1 significantly inhibited fibroblast invasion in vitro and attenuated lung fibrosis in vivo." (PMID 35980387, 2022). "CD274 expression was not induced by TGFβ in Population 1, in contrast to observations reported for normal human lung fibroblasts and in idiopathic pulmonary fibrosis (IPF) models." (PMID 36009475, 2022).
cervical squamous cell carcinoma (39 papers, 2016 to 2026). A squamous cell carcinoma arising from the cervical epithelium. "It has been shown that up to 70% of cervical squamous cell carcinoma (SCC) tissues have amplification of CD274 and PDCD1LG2 that encode PD‐L1 and PD‐L2, respectively." (PMID 40908776, 2025). "Through further analysis of cervical squamous cell carcinoma data in the TCGA database (n = 253), the expression of PD-L1 (CD274) was positively correlated with CD8A." (PMID 39489086, 2024).